VANGL2 (VANGL planar cell polarity protein 2)
Description:
Involved in the control of early morphogenesis and patterning of both axial midline structures and the development of neural plate. Plays a role in the regulation of planar cell polarity, particularly in the orientation of stereociliary bundles in the cochlea. Required for polarization and movement of myocardializing cells in the outflow tract and seems to act via RHOA signaling to regulate this process. Required for cell surface localization of FZD3 and FZD6 in the inner ear (By similarity).
Synonyms: KIAA1215; STB1; LTAP; LPP1; STBM; STBM1; MGC119403; MGC119404
Tractability: Antibody: its Gene Ontology location is reachable by antibodies, with high confidence; UniProt places it where antibodies can reach, with medium confidence; UniProt predicts a signal peptide or a membrane-spanning region. PROTAC: ubiquitination databases record sites on it; its protein half-life has been measured.
Gene: Protein-coding gene on chromosome 1 (160,400,564 to 160,428,678, forward strand). Ensembl gene ENSG00000162738.
Subcellular location: Cell membrane
Pathways (Reactome):
Signal Transduction: Asymmetric localization of PCP proteins; PCP/CE pathway; RND1 GTPase cycle; RND2 GTPase cycle; RND3 GTPase cycle
Gene Ontology:
Molecular function: protein binding
Biological process: apical protein localization; cell migration involved in kidney development; dopaminergic neuron axon guidance; establishment of planar polarity; heart looping; neural tube closure; non-motile cilium assembly; serotonergic neuron axon guidance; Wnt signaling pathway, planar cell polarity pathway; regulation of synapse pruning
Cellular component: apical plasma membrane; cell-cell junction; lateral plasma membrane; plasma membrane; apical cytoplasm; basolateral plasma membrane; cell periphery; cell pole; COPII-coated ER to Golgi transport vesicle; glutamatergic synapse; membrane; postsynaptic density membrane; stress fiber
Genetic constraint (gnomAD): Loss-of-function variants: 14 observed, 51.34 expected, observed/expected ratio (o/e) 0.27, 90% interval 0.18 to 0.43. The upper end of that interval is the gene's LOEUF score, 0.43, which puts it in group 1 of 6, group 1 being the genes least tolerant of losing a copy. Missense variants: 533 observed, 720.16 expected, observed/expected ratio (o/e) 0.74, 90% interval 0.69 to 0.8. Synonymous variants: 295 observed, 303.73 expected, observed/expected ratio (o/e) 0.97, 90% interval 0.88 to 1.07.
Homologues: Orthologues: chimpanzee VANGL2 (100% identical), macaque VANGL2 (99% identical), pig VANGL2 (99% identical), rabbit VANGL2 (99% identical), mouse Vangl2 (99% identical), rat Vangl2 (99% identical), guinea pig VANGL2 (99% identical), dog VANGL2 (91% identical), tropical clawed frog vangl2 (91% identical), zebrafish vangl2 (77% identical), Drosophila melanogaster Vang (48% identical), Caenorhabditis elegans vang-1 (32% identical). Paralogues in human: VANGL1 (73% identical).
Diseases named in the same sentence as VANGL2 in open-access papers:
VANGL2 is named in the same sentence as 95 diseases in open-access papers, as found by Europe PMC text mining. Sharing a sentence is not in itself a finding about the gene and the disease. The quoted sentences say what the papers report.
craniorachischisis (20 papers, 2010 to 2024). Craniorachischisis is the most severe form of neural tube defect in which both the brain and spinal cord remain open to varying degrees. "For example, homozygous core PCP pathway mutations like Vangl2 or Celsr1 usually result in the severe neural tube defect, craniorachischisis, whereas the Atmin homozygotes show exencephaly, a different neural tube closure defect." (PMID 24852369, 2014). "Two separate mutations in Sec24b also disrupt Vangl2 trafficking resulting in similar craniorachischisis phenotypes." (PMID 22363783, 2012). "Sequence analysis has not been success thus far in identifying the mutations in human Vangl2 gene in patients with craniorachischisis, although the Vangl2 mutation was identified in stillborn or miscarried fetuses with neural-tube defects." (PMID 21864354, 2011). "Craniorachischisis occurs following mutation of Sec24b, a protein recently shown to affect membrane localisation of Vangl2." (PMID 20704721, 2010). "Consistent with this hypothesis, mutations in sec24b, which encodes an ER transport protein that is required for Vangl2 movement to the plasma membrane, result in craniorachischisis similar to Lp." (PMID 22363783, 2012). "We found that reduced sulfation of glycosaminoglycans interacts with heterozygosity for the Lp allele of Vangl2 (a core PCP gene), to cause craniorachischisis in cultured mouse embryos, with rescue by exogenous sulphate." (PMID 34842271, 2022). "Homozygous Ptk7 deleterious variants in the mouse disrupted normal NTC, resulting in embryos with craniorachischisis; while fetuses that were doubly heterozygous for Ptk7 and Vangl2 presented with spina bifida." (PMID 30689296, 2019). "Among craniorachischisis cases, about 20% have potentially deleterious variants in single PCP genes (VANGL2, CELSR1, SCRIB or DACT1)." (PMID 30134561, 2018). "In yet another type of digenic cause, high frequencies of craniorachischisis are found in mutants that are double heterozygotes for mutations at two PCP genes of different gene families (e.g., Vangl2;Celsr1, Vangl2;Dvl2, Vangl2;Scrib, or Celsr1;Scrib)." (PMID 30134561, 2018). "The Lp allele acts in a gene-dosage dependent manner such that heterozygous animals (Vangl2+/Lp) are viable but exhibit a looped tail, while homozygous embryos (Vangl2Lp/Lp, Lp mutant) die in utero due to craniorachischisis." (PMID 25596276, 2015). "Vangl2neo/neo mice, which retain the neomycin selection cassette within the construct, were hypomorphic for Vangl2, with 2/3 displaying craniorachischisis and 1/3 spina bifida only." (PMID 25521757, 2014). "Vangl2, Scrib and Celsr1 are among the most intensively studied mouse PCP genes, each of which causes craniorachischisis in homozygous mutants." (PMID 25128525, 2014). "Several of the mouse mutants with craniorachischisis have mutations that disrupt core components of the PCP pathway, including Celsr1, Vangl1, Vangl2, Fzd3, Fzd6, Dvl1, Dvl2 and Dvl3." (PMID 25128525, 2014). "A similarly low percentage of Vangl2/PTK7 double heterozygotes exhibit craniorachischisis but nevertheless, there is ample evidence that PTK7 makes an important contribution to the PCP signaling pathway." (PMID 24852369, 2014). "Most recently, mutation of Sec24b has been shown to cause craniorachischisis, and Sec24b affects PCP through regulation of Vangl2 protein trafficking." (PMID 20704721, 2010). "Disruption of Wnt5a can also lead to craniorachischisis, and Wnt5a genetically interacts with Vangl2 mutants." (PMID 20704721, 2010). "Consequently, Vangl2−/− embryos develop fully penetrant craniorachischisis, precluding analysis of Vangl2 roles in spinal neurulation." (PMID 29590636, 2018). "However, Wnt5a−/−;Vangl2+/Lp embryos exhibit craniorachischisis with a penetrance of 100%, implicating Wnt5a in PCP regulation." (PMID 25596276, 2015).
craniorachischisis (continued). "Genetic interaction between Wnt5a and Ltap/Vangl2 could enhance the penetrance of neural tube closure and all Wnt5a-/-; LtapLp/+ mice exhibited craniorachischisis." (PMID 21864354, 2011). "Interestingly, as is the case with the craniorachischisis phenotype in homozygosity, the failure of NT dorsal fusion is fully penetrant in Vangl2+/Lp embryos, and we believe that only in the most severe cases, where the affected area is too large, an open spina bifida would develop." (PMID 37589570, 2023). "However, this hypothesis might also predict that Ptk7;Vangl2 double heterozygotes should have a higher craniorachischisis frequency than Ptk7 homozygotes, whereas we and others have observed the opposite." (PMID 25128525, 2014). "However, the phenotypes associated with the disruption of Vangl2 (ablation, looptail mutations) are characterized by serious neural issues such as craniorachischisis and other severe neural tube defects, a phenotype not observed in NHERF1-/- or Celsr2/3-/- animals." (PMID 27055101, 2016). "A potential role of PCP in NTDs came to light following positional cloning of Vangl2 in the loop-tail mouse mutants that exhibit a severe NTD, craniorachischisis." (PMID 21864354, 2011). "Several of the mouse craniorachischisis mutants affect genes that are homologues of these core PCP proteins, including Vangl1 and Vangl2 (strabismus/van gogh homologues), Celsr1 (flamingo/starry night), Frizzled and Dishevelled." (PMID 20704721, 2010). "In some examples, mutants are homozygous at only one PCP gene (e.g., Vangl2, Celsr1, Scrib or Sec24b) and all embryos have craniorachischisis; heterozygotes do not." (PMID 30134561, 2018). "The second difference between the putative p.(Arg135Trp) homozygous patients and Vangl2 mutant mice is the absence of any NTD in the probands, particularly craniorachischisis which is fully penetrant in Lp mutants due to failure of CE." (PMID 37815931, 2024). "We conclude that craniorachischisis originates through failure of Closure 1 in homozygotes for all three PCP mutants, but that ScribCrc/+ embryos do not exhibit delayed closure, unlike Celsr1 or Vangl2 heterozygotes." (PMID 25128525, 2014).
breast cancer (18 papers, 2010 to 2025). A primary or metastatic malignant neoplasm involving the breast. "We observed that loss of VANGL2 expression significantly impairs breast cancer cell migration, indicated by the reduced ability of VANGL2 knockdown cells to migrate into a scratch made in the cellular monolayer." (PMID 37147680, 2023). "Both Vangl1 and Vangl2 are found to be overexpressed in breast cancers and are associated with poor prognosis and have been implicated in tumor growth or cancer cell migration." (PMID 33990333, 2021). "In SKBR7 breast cancer cells, we found a poor recruitment of VANGL2 at the plasma membrane, likely due to the loss of cell junctions." (PMID 26754771, 2016). "Here we show that the archetypal Wnt/PCP protein VANGL2 is overexpressed in basal breast cancers, associated with poor prognosis and implicated in tumour growth." (PMID 26754771, 2016). "Furthermore, increased levels of VANGL2 are linked to higher rates of recurrence and reduced metastasis-free survival in breast cancer patients." (PMID 39968094, 2025). "In this mouse model of breast cancer, we observed that overexpressed VANGL2 caused a dramatic reduction in tumour latency, since tumour occurrence was detectable 7 weeks post graft with VANGL2-overexpressed cells, whereas 14 weeks were required for GFP-expressed control cells." (PMID 26754771, 2016). "Therefore, we interrogated whether loss of Vangl2 impacts cell motility of diverse breast cancer cells of distinct molecular subtypes: triple-negative BT549, MDA-MB-231 and MDA-MB-468, HER2-positive SkBr3 and NDL, and ER/PR-positive MCF7 and T47D." (PMID 37147680, 2023). "The MMTV-NDL murine model was selected based on our observations that Vangl2 is highly expressed in tumors from this model and Vangl2 overexpression was observed in breast cancer patient tumors of all molecular subtypes." (PMID 37147680, 2023). "The impact of Wnt/PCP suppression on mammary tumor growth and metastasis was assessed by determining the effect of conditional Vangl2 knockout on the MMTV-NDL mouse mammary tumor model." (PMID 37147680, 2023). "In contrast, luminal B and HER2-dependent VANGL2/NOS1AP-amplified breast cancers show over-expression of VANGL2 mRNA only occasionally." (PMID 36675340, 2023). "Consistently, we find that Vangl2 expression is highly heterogeneous across a panel of human and murine breast cancer cell lines encompassing several molecular subtypes as well as tumors from two commonly employed genetic models of murine mammary carcinoma." (PMID 37147680, 2023). "We observed that Vangl2 knockdown suppresses the motility of all breast cancer cell lines examined, and overexpression drives the invasiveness of collectively migrating MMTV-PyMT organoids." (PMID 37147680, 2023). "In an exploration of cell line models, two of the four breast cancer cell line models with amplifications in VANGL2, NOS1AP and SCRIB display sensitivity to drugs inhibiting acyl-transferase porcupine interfering with the WNT pathway." (PMID 36675340, 2023). "NOS1AP mRNA is not consistently over-expressed in any of the four sub-types in VANGL2- or NOS1AP-amplified breast cancers." (PMID 36675340, 2023). "Our findings that high expression of Vangl1 or Vangl2 results in a hyper-protrusive leading edge suggest that Vangl localizes to the protrusive leading-edge membrane of leader cells in migrating breast cancer cell cohorts to regulate the cytoskeleton." (PMID 37147680, 2023). "The mRNA expression of PCP-related genes VANGL2, NOS1AP, SCRIB, WNT11 and SMURF2 in VANGL2- or NOS1AP-amplified breast cancers (most cases are co-amplified) is heterogeneous in molecular sub-types." (PMID 36675340, 2023). "Basal breast cancers frequently display over-expression of VANGL2 and SCRIB independently of the copy number status of their genes." (PMID 36675340, 2023). "We observe Vangl1 and Vangl2 localization to the leading edge of migrating MDA-MB-231 breast cancer cells within actin-rich migratory protrusions." (PMID 37147680, 2023).
breast cancer (continued). "Similar to Vangl2, Wnt5a ligand expression is heterogeneous among breast cancer cell lines and genetic models of murine mammary carcinoma." (PMID 37147680, 2023). "VANGL2 mRNA is over-expressed in many luminal A VANGL2/NOS1AP-amplified breast cancers and in most basal VANGL2- or NOS1AP-amplified breast cancers." (PMID 36675340, 2023). "We employed immunofluorescence microscopy to assess the localization of endogenous and ectopically expressed Wnt/PCP components Vangl1 and Vangl2 in singly and collectively migrating breast cancer cells." (PMID 37147680, 2023). "Consistent with findings from mammalian development, Wnt5a stimulation phosphorylates Vangl2 at critical functional residues across a panel of breast cancer cell lines and loss of VANGL2 suppresses Dvl2 phosphorylation." (PMID 37147680, 2023). "We demonstrate that Vangl2 is critical for efficient metastasis but dispensable for primary tumor growth in ErbB2-induced mouse mammary tumors." (PMID 37147680, 2023). "Breast cancer cells overexpressing Vangl1 or Vangl2 exhibit increased motility and Dvl2 phosphorylation compared to cells transduced with control lentivirus and display a distinctive hyper-protrusive leading-edge morphology." (PMID 37147680, 2023). "We observed that Vangls localize to the leading edge of singly and collectively migrating breast cancer cells and that high expression of Vangl1 or Vangl2 in leader cells results in a hyper-protrusive leading edge." (PMID 37147680, 2023). "Some studies suggest that Vangl2 is also a scaffold for mediators of breast cancer cell proliferation." (PMID 35646914, 2022). "In human breast cancer cells, prior studies have shown that Vangl1 and Vangl2 promote cancer cell proliferation or migration." (PMID 33990333, 2021). "Our data shows that two of the Wnt/PCP genes (WNT11 and VANGL2) are targets of miR-1291 and both have been reported to promote cell motility and metastasis in breast cancer." (PMID 33343622, 2020). "SQSTM1 is a key component and player in VANGL2–JNK signaling pathway and this signaling pathway is associated with the proliferation of breast cancer cells." (PMID 31311202, 2019). "For example, the scaffold p62 protein cooperates with the Wnt/PCP protein VANGL2 and recruits JNK to VANGL2, which is required for tumour growth in breast cancer." (PMID 28968743, 2017). "Results obtained in cultured cell lines were confirmed in breast cancer PDX-derived cells that grow at higher cell proliferation rate in the context of VANGL2 overexpression." (PMID 26754771, 2016). "To address the role of VANGL2 in breast cancer, we first examined VANGL2 messenger RNA expression in a large data set of 2,687 invasive breast cancers." (PMID 26754771, 2016). "Thirty breast cancer PDXs were characterized for VANGL2 and p62/SQSTM1 expression as well as JNK activation levels with western blot analysis." (PMID 26754771, 2016). "Altogether, we provide compelling evidence that, in breast cancer cells, WNT5A–VANGL2 signalling requires the integrity of the VANGL2–p62/SQSTM1 complex to associate with and phosphorylate JNK." (PMID 26754771, 2016). "The presence of the VANGL2–p62/SQSTM1 complex in breast cancer PDX protein extracts was confirmed by VANGL2 immunoprecipitation followed by western blot analysis." (PMID 26754771, 2016). "Altogether, these data suggest that the VANGL2–p62/SQSTM1 colocalization occurs in part in late endosomal compartments in breast cancer cells and is regulated by cell junction formation." (PMID 26754771, 2016). "In breast cancer PDXs, a good correlation was found between levels of VANGL2 and phosphorylated JNK." (PMID 26754771, 2016). "The functional cooperation between VANGL2 and p62/SQSTM1 was confirmed in vitro in anchorage-independent assays by the apparent increase in tumorigenicity of breast cancer cells ectopically co-expressing VANGL2 and p62/SQSTM1." (PMID 26754771, 2016).